ENAM (enamelin)
Description:
Involved in the mineralization and structural organization of enamel. Involved in the extension of enamel during the secretory stage of dental enamel formation.
Synonyms: ADAI; AI1C; AIH2
Tractability: Antibody: UniProt places it where antibodies can reach, with medium confidence; UniProt predicts a signal peptide or a membrane-spanning region; its Gene Ontology location is reachable by antibodies, with medium confidence. PROTAC: ubiquitination databases record sites on it.
Gene: Protein-coding gene on chromosome 4 (70,628,744 to 70,646,824, forward strand). Ensembl gene ENSG00000132464.
Subcellular location: Secreted, extracellular space, extracellular matrix
Pathways (Reactome):
Metabolism of proteins: Post-translational protein phosphorylation; Regulation of Insulin-like Growth Factor (IGF) transport and uptake by Insulin-like Growth Factor Binding Proteins (IGFBPs)
Gene Ontology:
Molecular function: protein binding; structural constituent of tooth enamel
Biological process: ameloblast differentiation; amelogenesis; positive regulation of enamel mineralization
Cellular component: endoplasmic reticulum lumen; extracellular matrix
Genetic constraint (gnomAD): Loss-of-function variants: 16 observed, 27.25 expected, observed/expected ratio (o/e) 0.59, 90% interval 0.4 to 0.89. The upper end of that interval is the gene's LOEUF score, 0.89, which puts it in group 3 of 6, group 1 being the genes least tolerant of losing a copy. Missense variants: 1,287 observed, 1,349.1 expected, observed/expected ratio (o/e) 0.95, 90% interval 0.91 to 1. Synonymous variants: 443 observed, 466.83 expected, observed/expected ratio (o/e) 0.95, 90% interval 0.88 to 1.03.
Homologues: Orthologues: chimpanzee ENAM (99% identical), macaque RUFY3 (91% identical), dog ENAM (78% identical), pig ENAM (73% identical), rabbit ENAM (69% identical), rat Enam (62% identical), guinea pig ENAM (62% identical), mouse Enam (62% identical), tropical clawed frog enam (20% identical).
Diseases named in the same sentence as ENAM in open-access papers:
ENAM is named in the same sentence as 29 diseases in open-access papers, as found by Europe PMC text mining. Sharing a sentence is not in itself a finding about the gene and the disease. The quoted sentences say what the papers report.
amelogenesis imperfecta (12 papers, 2009 to 2025). Amelogenesis imperfecta (AI) represents a group of developmental conditions affecting the structure and clinical appearance of the enamel of all or nearly all the teeth in a more or less equal manner, and which may be associated with morphologic or biochemical changes elsewhere in the body. "Both frameshifts occur in the terminal exon of ENAM and are associated with amelogenesis imperfecta (AI), a condition affecting enamel formation, resulting in truncated enamelin protein production." (PMID 41210864, 2025). "ENAM mutations cause autosomal dominant or recessive amelogenesis imperfecta (AI) and show a dose effect: enamel malformations are more severe or only penetrant when both ENAM alleles are defective." (PMID 31478359, 2019). "In addition to susceptibility to caries, mutations in the ENAM gene have been described to cause enamel defects such as hypoplasia (thinner and more irregular enamel) and hypomineralization linked to Amelogenesis imperfecta (AI) disorders." (PMID 28902892, 2017). "In the light of the data presented here, the pig model appears to be less than ideal when trying to understand enamelin function in humans and other species, whether in relation to normal amelogenesis or in cases of enamelin-linked amelogenesis imperfecta." (PMID 22243266, 2011). "Several SNPs, for example, rs3796704 in the gene encoding enamelin (ENAM) or rs17878486 in AMELX, were previously associated with various dental problems, such as amelogenesis imperfecta or molar-incisor hypomineralization, despite being in non-coding regions." (PMID 36422720, 2023). "One individual had a previously reported heterozygous variant in the ENAM gene, (ENST00000396073.3: c.1259_1260insAG, p.Pro422ValfsTer27), associated with Amelogenesis imperfecta (AI) ‐ hypoplastic autosomal dominant." (PMID 36910591, 2023). "Mutations in genes involved in enamel formation, such as enamelin (ENAM), amelogenin (AMELX), matrix metalloproteinase-20 (MMP-20) and kallikrein-related peptidase (KLK4), were associated with amelogenesis imperfecta." (PMID 28697775, 2017). "Mutations in the genes for amelogenin (AMELX), enamelin (ENAM), enamelysin (MMP20), and kallikrein 4 (KLK4) are known to cause defects in enamel that are collectively referred to as amelogenesis imperfectas." (PMID 19730686, 2009).
dental caries (11 papers, 2016 to 2024). The decay of a tooth, in which it becomes softened, discolored, and/or porous. "Some genome-wide association studies in patients with dental caries from European Americans showed the role of types of ENAM genes in the formation of dental caries and aroused greater interest in the study of single nucleotide polymorphisms in the ENAM gene." (PMID 36624859, 2022). "Of all polymorphisms, there was a significant association only between ENAM rs3796704 polymorphism and dental caries susceptibility." (PMID 32375748, 2020). "Specific alleles of ENAM are also associated with high susceptibility to dental caries and the expression level of enamelin appears to be determinant for the structure and quality of enamel." (PMID 28603502, 2017). "Exogen 10 of the ENAM gene seems to plays a key role in causing dental caries." (PMID 36624859, 2022). "Also, one study reported an elevated risk of ENAM rs3796704 polymorphism and another study showed an elevated risk of ENAM rs3796703 polymorphism in dental caries patients compared with controls." (PMID 32375748, 2020). "Therefore, there was a significant association between ENAM rs3796704 polymorphism and dental caries susceptibility." (PMID 32375748, 2020). "There was an association between ENAM rs3796704 polymorphism and the risk of dental caries." (PMID 32375748, 2020). "In addition, the sensitivity analysis confirmed the effect of ethnicity and type of control group on the association of ENAM rs3796704 and risk of dental caries." (PMID 32375748, 2020). "Further research on the ENAM gene has led to the identification of nonsynonymous mononucleotide polymorphisms (rs7671281 and rs3796704) that may be associated with the formation of dental caries." (PMID 36624859, 2022). "This meta-analysis evaluated the association of LTF, ENAM, and AMELX polymorphisms with dental caries susceptibility." (PMID 32375748, 2020). "The association between the mutations of LTF, ENAM, and AMELX genes and dental caries susceptibility has been shown in some studies." (PMID 32375748, 2020). "Both ENAM rs3796704 and AMELX rs17878486 polymorphisms had a significant association with dental caries risk in the Caucasian ethnicity and the studies including caries-free control group." (PMID 32375748, 2020). "This meta-analysis assessed the association between the common polymorphisms of LTF, ENAM, and AMELX and the risk of dental caries." (PMID 32375748, 2020). "For instance, in Polish children, the prevalence of the AG genotype of the Enamelin (ENAM) gene (rs12640848) was higher in subjects with dental caries compared to that in controls." (PMID 31133012, 2019). "Several previous studies have identified an association between several genes and dental caries, including genes related to enamel formation such as AMBN, AMELX, and ENAM; taste receptor genes such as TAS2R38, TAS1R2; immune-related genes such as HLA; and saliva genes such as MUC5B, PRH1." (PMID 38414691, 2024). "Previous studies have reported that ENAM genes including rs3796704 and rs7671281 may affect the microstructure of tooth enamel, which may lead to caries and may play a role in dental caries." (PMID 36624859, 2022). "Therefore, the aim of the present study was to investigate the differences between caries-free individuals and those with dental caries in terms of two genes associated with dental caries, i.e., AMELX and ENAM." (PMID 36624859, 2022). "Therefore, there was a significant association between both polymorphisms of ENAM rs3796704 and AMELX rs17878486 and dental caries susceptibility in the Caucasian ethnicity and studies including caries-free individuals as the control group." (PMID 32375748, 2020). "However, subgroup analysis showed an association between ENAM rs3796704 and AMELX rs17878486 polymorphisms and dental caries susceptibility in the Caucasian ethnicity and studies including caries-free individuals as the control group." (PMID 32375748, 2020).
dental caries (continued). "On the other hand, according to the results, the relationship between single nucleotide polymorphisms of ENAM gene and the absence of dental caries was close to be significant and may become significant with increase in the sample size in further studies." (PMID 36624859, 2022). "Studies have reported that ENAM rs12640848 may be related to hypomineralization and dental caries, therefore it is important to study the variation in order to understand the molecular pathogenesis of tooth enamel formation, a stage with a greater susceptibility to fluoride overexposure." (PMID 32178265, 2020). "Thus, our results may contribute to the genotypic identification of ENAM as a protective factor against dental caries and to the molecular characterization of the dental enamel at the exposure to high concentrations of fluorides." (PMID 32178265, 2020). "Genetic association studies of dental caries have suggested that caries may be influenced by variations in enamel formation genes, such as ameloblastin (AMBN), amelogenin (AMELX), enamelin (ENAM), matrix metalloproteinase 20 (MMP20), tuftelin (TUFT1), and tuftelin-interacting protein 11 (TFIP11)." (PMID 29163197, 2017). "Three prevalent genes are reportedly involved in development of dental caries namely the lactotransferrin (LTF), enamelin (ENAM), and amelogenin X (AMELX)." (PMID 32375748, 2020).
enamel hypoplasia (3 papers, 2014 to 2017). "Individuals with both ENAM alleles defective typically present with severe enamel hypoplasia, while individuals with one allele mutated have localized, pitted defects and/or horizontal grooves on their teeth." (PMID 24603688, 2014). "Based upon the analysis of the knockout mouse model, we determined the temporal and spatial expression of enamelin, characterized the structural and cellular defect of amelogenesis, which provided the pathologic basis of enamel hypoplasia." (PMID 24603688, 2014). "Therefore, it is not surprising that enamel hypoplasia has been observed in many breeds, although only one other mutation causing a heritable enamel hypoplasia has been characterized to date, an ARAI involving the enamelin gene (ENAM) in Italian Greyhounds." (PMID 29201383, 2017).
renal clear cell carcinoma (2 papers, 2021 to 2022). "However, recent studies have found that the ENAM gene is associated with T classification and inhibits the proliferation of renal clear cell carcinoma and that WDR72 genomic variants are associated with distal tubular acidosis and rapid declines in renal function." (PMID 35875087, 2022).
Alzheimer disease (1 paper, 2021). A progressive, neurodegenerative disease characterized by loss of function and death of nerve cells in several areas of the brain leading to loss of cognitive function such as memory and language. "Eleven of those follow an autosomal-dominant inheritance pattern and span a wide range of phenotypes, including three genes linked to various dental issues (AMTN, ENAM, DSPP) and APP known to cause Alzheimer disease when duplicated." (PMID 33315133, 2021).
deficiencies (1 paper, 2016). "For example, hypoplastic or aplastic enamel deficiencies are produced by amelogenin (Amel), ameloblastin (Ambn), and enamelin (Enam) mutations, recapitulating defects in patients." (PMID 28111553, 2016).
dental disorders (1 paper, 2017). "Several polymorphisms, in particular in the non-collagenous extracellular matrix proteins of the tooth hard tissues, like enamelin, are involved in dental structure variation and defects and may be associated with dental disorders or susceptibility to caries." (PMID 28902892, 2017).
dental fluorosis (1 paper, 2020). A condition that results from excessive fluoride ingestion during tooth development, resulting in tooth discoloration ranging from white streaks to brown stains and cracks or pits in the tooth enamel. "The ENAM gene plays an important role in tooth enamel development and the etiology of dental fluorosis." (PMID 32178265, 2020).
osteosarcoma (1 paper, 2015). A usually aggressive malignant bone-forming mesenchymal neoplasm, predominantly affecting adolescents and young adults. "Furthermore, ectopic expression of Fam20A in the human osteosarcoma cell line U2OS, which produces Fam20C, but not Fam20A, significantly increased phosphorylation of V5-tagged OPN, ENAM and AMBN, without altering Fam20C expression levels." (PMID 25789606, 2015).
renal carcinoma (1 paper, 2021). A carcinoma arising from the epithelium of the renal parenchyma or the renal pelvis. "MTT assays further validated this observation, indicating that ENAM overexpression could also inhibit the proliferation of renal cancer cells." (PMID 33539322, 2021).
tumor (3 papers, 2021 to 2024). "Among them were genes associated with blood clotting (FGA, FGG) and genes associated with changes in the immune characteristics of a tumor (ENAM, IGFBP1, IL6)." (PMID 36028558, 2022). "Its interaction with immune cells in the tumor microenvironment renders ENAM as an underlying immunotherapy target in ccRCC." (PMID 33539322, 2021). "ENAM expression was evaluated in 72 paired tumor and paratumor samples, and its low expression was found in the tumor tissues." (PMID 33539322, 2021). "Experimental results showed that ENAM is lowly expressed in ccRCC tissues and could inhibit tumor proliferation." (PMID 33539322, 2021). "Among odontogenesis related genes, AMBN is specifically expressed in T3, other genes including ENAM, AMELX and AMELY are not expressed in all the tumor cells." (PMID 39223689, 2024).
cancer (1 paper, 2017). A tumor composed of atypical neoplastic, often pleomorphic cells that invade other tissues. "The Combo-1 and Combo-2 panels provide a few genes that already have their implication as putative biomarkers in other cancers and also suggest some novel genes like ENAM, whose role in cancer has not been investigated." (PMID 28349958, 2017).
ENAM also shares sentences with these, for which no sentence is quoted: asthma (1 paper); diabetes (1); genetic diseases (1); Hypoplastic amelogenesis imperfecta (1); leukemia (1); malocclusion (1); measles (1); metabolic disorders (1); otitis (1); pancreatic cancer (1); respiratory infections (1); rubella (1); syphilis (1); tetanus (1); type 2 diabetes (1); urinary tract infection (1); varicella (1).